HGF (hepatocyte growth factor)
Diseases named in the same sentence as HGF in open-access papers (continued):
Sharing a sentence is not in itself a finding about the gene and the disease.
proliferative diabetic retinopathy (2 papers, 2015 to 2019). Advanced retinopathy due to diabetes mellitus characterized by the formation of new vessels in the retina. "HGF was found to be increased in vitreous samples of patients with proliferative diabetic retinopathy and was higher in vitreous than in blood similar to our results." (PMID 25978399, 2015).
pulmonary edema (2 papers, 2020 to 2025). Accumulation of fluid in the lung tissues causing disturbance of the gas exchange that may lead to respiratory failure. "Studies have shown that MSCs can reduce pulmonary vascular permeability and alleviate pulmonary edema, partly through the secretion of growth factors such as angiopoietin-1 (Ang-1), keratinocyte growth factor (KGF), hepatocyte growth factor (HGF), and vascular endothelial growth factor (VEGF)." (PMID 41013838, 2025). "Severe pulmonary oedema was also detected in the septic mice, as revealed by lung weight/body weight (LW/BW) ratio, and this pulmonary oedema was abrogated by HGF in the CLP + HGF group." (PMID 32795289, 2020).
pulmonary embolism (2 papers, 2015 to 2021). The obstruction of the pulmonary artery or one of its branches by an embolus, sometimes associated with infarction of the lung. "In addition to being markers of inflammation and angiogenesis, HGF is associated with thrombosis and pulmonary embolism, while CHI3L1 is known to promote coagulation by inducing the expression of TF." (PMID 34262673, 2021).
rash (2 papers, 2017 to 2021). "EGFR ligands like epiregulin (EREG), amphiregulin (AREG), and hepatocyte growth factor (HGF) were investigated as biomarkers for skin rash and found to be inversely proportional to grades of skin toxicity." (PMID 34012511, 2021). "Because the association between HGF level and OS of the patients was only significant in patients who had developed EGFRI-induced skin rash, we further analyzed the correlation of the plasma concentrations of HGF and amphiregulin with this rash." (PMID 28456787, 2017). "The mechanism behind the correlation between HGF levels and skin rash is not completely understood so far." (PMID 28456787, 2017). "In the subgroup of patients with skin rash, the mean OS time was 299 days (SE: 11.2) for patients with low HGF levels (≤ 1220 pg/ml) and 240 days (SE: 14.5) for patients with high levels (> 1220 pg/ml)." (PMID 28456787, 2017). "The plasma concentration of HGF was significantly inversely correlated with skin rash (p-value = 0.00124)." (PMID 28456787, 2017). "It should be noted that in our subgroup of patients who developed no skin rash a trend towards an association between plasma levels of HGF and OS was also visible." (PMID 28456787, 2017). "This allowed to investigate whether the increased OS in patients with low plasma concentrations of HGF was specific for patients with EGFRI-induced skin rash or rather a general observation for all patients." (PMID 28456787, 2017). "This suggests that, in addition to being predictive for EGFRI efficacy, the skin rash might also partially be a prognostic marker, which would match our observations for HGF." (PMID 28456787, 2017). "We also observed a significant inverse correlation between HGF levels and severity of EGFRI-induced rash." (PMID 28456787, 2017). "This compensation of EGFR inhibition by HGF/MET signaling might also happen in skin cells and could explain why higher plasma concentrations of HGF correlate with less severe EGFRI-induced skin rash." (PMID 28456787, 2017). "However, the correlation between plasma concentration of HGF and OS was only significant in the subgroup of patients who had developed skin rash and not in the group without rash." (PMID 28456787, 2017). "We observed a significant inverse correlation between the plasma concentration of HGF and overall survival in patients with an inhibitor-induced rash (p-value = 0.0075; mean overall survival low HGF: 299 days, high HGF: 240 days) but not in patients without rash." (PMID 28456787, 2017).
Renal cyst (2 papers, 2017 to 2021). A fluid filled sac in the kidney. "The ligand to c-MET, hepatocyte growth factor (HGF) is thought to mediate human renal cyst formation." (PMID 28209203, 2017). "While, during the progression of ADPKD, the cleaved PC1 tail could co-activate STAT1 that had been activated by IFN, STAT3 that had been activated by IL-6, EGF, HGF (hepatocyte growth factor) signaling, STAT6 that had been activated by IL4, IL-13 signaling to promote renal cyst growth and fibrosis." (PMID 34199002, 2021).
septic shock (2 papers, 2015 to 2021). Shock caused by infection; frequently caused by gram negative bacteria, although some cases have been caused by other bacteria, viruses, fungi, and protozoa; characterized by fever, chills, tachycardia, tachypnea, and hypotension. "Additionally, the septic shock patients exhibited a remarkable increase in the levels of IP-10 and HGF." (PMID 25928796, 2015).
soft tissue sarcoma (2 papers, 2012 to 2015). A malignant neoplasm arising from muscle tissue, adipose tissue, blood vessels, fibrous tissue, or other supportive tissues excluding the bones. "Our results were obtained by up-to-date biomarker assays and provide first comprehensive epidemiologic data for ongoing and upcoming clinical trials with MET/HGF inhibitors in soft tissue sarcomas and GIST." (PMID 25844809, 2015). "Hepatocyte growth factor (HGF) is produced by a large number of tumors (including carcinomas, soft tissue sarcoma, and hematopoietic malignancies) and is implicated in tumor angiogenesis." (PMID 23320019, 2012). "An overexpression of the MET ligand HGF could be found—among others—in malignant pleural mesotheliomas, gastric carcinomas, gliomas as well as in some soft tissue sarcomas." (PMID 25844809, 2015). "In this study we aimed at investigating the HGF/MET axis in a comprehensive and well characterized cohort of various adult-type soft tissue sarcomas and GIST." (PMID 25844809, 2015). "However, a systematic and comprehensive prevalence study of MET and HGF alterations in soft tissue sarcomas has not yet been published." (PMID 25844809, 2015).
Splenomegaly (2 papers, 2014 to 2015). Abnormal increased size of the spleen. "The development of splenomegaly has also been associated with specific cytokines including MIG, HGF, and IL-1RA." (PMID 26538823, 2015). "IL-2R and IL-12 were associated with transfusion needs and HGF, MIG, and IL-1RA were associated with marked splenomegaly." (PMID 26538823, 2015). "Altogether, in AML and possibly in CML, the level of HGF in serum strongly correlates with biological parameters considered to reflect tumoural burden, especially leukocyte counts, splenomegaly and vascular syndrome." (PMID 25119536, 2014). "Subsequent studies analysedthe levels of 30 cytokines in the plasma of PV and PMF patients: HGF was increased in both PV and PMF, compared to healthy donors, and HGF was correlated with leukocyte countsin PV and PMF, and also with splenomegaly in PMF." (PMID 25119536, 2014).
Thrombocytopenia (2 papers, 2021 to 2025). A reduction in the number of circulating thrombocytes. "Supervised machine learning spotlighted IL-10 in P. vivax-mediated thrombocytopenia and provided evidence for a potential signaling route involving IL-8 and HGF." (PMID 33791239, 2021).
tongue tumor (2 papers, 2020 to 2021). "To further explore the downstream molecular mechanism of HGF overexpression, we performed RNA-seq using tongue tumor tissues harvested from Wt and HGF-Tg mice." (PMID 34970484, 2021). "In this study, we used HGF-overexpression transgenic mice (globally expressed) and tongue tumor models induced by 4NQO to explore the role of HGF/c-Met signaling in oral tumorigenesis." (PMID 34970484, 2021). "At week 24, most 4NQO-treated mice showed typical pathological features of tongue tumors, with the tumor volume of the HGF-Tg group being significantly smaller." (PMID 34970484, 2021). "Therefore, our data suggested that inhibition of the MAPK and PI3K-AKT pathways may play a role in the progression of tongue tumor of HGF-Tg mice." (PMID 34970484, 2021).
unstable angina (2 papers, 2017 to 2022). "Percent change in HGF at days 0–12 and the development of unstable angina directly correlated in group 2 (R = -0.5; p = 0.03)." (PMID 28558042, 2017).
usual interstitial pneumonia (2 papers, 2013 to 2017). "We have demonstrated previously the presence of bone marrow derived, hepatocyte growth factor (HGF) -secreting, stem cells in human lung tissue from patients with usual interstitial pneumonia." (PMID 28827799, 2017). "We studied the presence, origin and antifibrotic properties of HGF-expressing stem cells in usual interstitial pneumonia." (PMID 23840329, 2013).
vascular tumor (2 papers, 2012 to 2022). "Apart from the PI3K/AKT/MTOR and RAS/RAF/ERK signaling pathways, other signaling pathways are also involved in VAs: VEGF-A/VEGFR2 signaling and PDGFB/PDGFRB Signaling Pathway in vascular tumors (IH) and HGF [hepatocyte growth factor])/c -Met signaling in glomuvenous malformations (GVMs)." (PMID 36293054, 2022).
viral hepatitis (2 papers, 2019 to 2022). An acute or chronic inflammation of the liver parenchyma caused by viruses. "Of the five transcripts significantly up-regulated in response to EECP administration in female mice, HGF has been reported to ameliorate liver inflammation during viral hepatitis." (PMID 31998465, 2019).
abscess (1 paper, 2021). An inflammatory process characterized by the accumulation of pus within a newly formed tissue cavity which is the result of a bacterial, fungal, or parasitic infection or the presence of a foreign body. "The proteins HGF and PDGFB were both involved in fibrosis, which is especially interesting given that fibrosis is required to encapsulate the SAC and immune cells around SAC to form an abscess." (PMID 34832602, 2021).
Achalasia (1 paper, 2022). A disorder of esophageal motility characterized by the inability of the lower esophageal sphincter to relax during swallowing and by inadequate or lacking peristalsis in the lower half of the body of the esophagus. "This increased activation of satellite cells has been recently proposed to be linked to the activity of FAPs secreting HGF in mice, which may lead to satellite cell dysfunctions and the progressive dysphagia observed both with age (achalasia) as well as in several pathologies (OPMD, IBM, DM1)." (PMID 36197469, 2022).
acute leukemia (1 paper, 2022). A clonal (malignant) hematopoietic disorder with an acute onset, affecting the bone marrow and the peripheral blood. "HGF levels in patients with acute leukemia are higher than those in healthy individuals, and higher HGF expression is associated with lower survival rates." (PMID 36407095, 2022).
acute lymphoid leukaemia (1 paper, 1996). "In contrast, the HGF mRNA was less abundantly expressed in acute lymphoid leukaemia (ALL)." (PMID 8554973, 1996).
adenovirus infection (1 paper, 2021). "To optimize the efficiency of adenovirus infection in BMSCs, we calculated the percentage of GFP-positive cells in BMSCs-HGF and BMSCs-GFP at different MOIs." (PMID 35003786, 2021).
androgenetic alopecia (1 paper, 2025). "Additionally, research on the use of the herbal treatment Wubao Hair Growth Tincture, based on the HGF/c-Met signaling pathway for treating androgenetic alopecia, has shown that this method can balance hormones by activating the HGF/c-Met signaling pathway, thus treating androgenetic alopecia." (PMID 40790388, 2025).
aneurysm (1 paper, 2022). Bulging or ballooning in an area of an artery secondary to arterial wall weakening. "In previous studies, VWF was found to be expressed in aneurysm tissue and colocalized with hepatocyte growth factor (HGF) in the most severe part of the aneurysm-injured wall." (PMID 35637715, 2022).
ankylosing spondylitis (1 paper, 2024). An autoimmune chronic inflammatory disorder characterized by inflammation in the vertebral joints of the spine and sacroiliac joints. "In line with our results, the increased serum levels of HGF, a growth factor involved in bone metabolism, were also demonstrated in patients with ankylosing spondylitis treated with GCs compared with those without GC therapy." (PMID 39744635, 2024).
aseptic meningitis (1 paper, 2015). Inflammation of the membranes surrounding the brain and spinal cord without a bacterial pathogen. "Consistent with previous observations regarding presence and quality of HGF in body fluids during infection, we found a significant difference in CSF-derived HGF concentrations between samples from patients with community-acquired septic meningitis and samples from those with aseptic meningitis." (PMID 26408034, 2015).
bacterial meningitis (1 paper, 2008). Inflammation of the membranes surrounding the brain and spinal cord due to a bacterial infection. "Strong increases of HGF concentrations in cerebrospinal fluid (CSF) are only present in patients with acute bacterial meningitis." (PMID 24179347, 2008).
basal cell carcinoma (1 paper, 2013). A carcinoma involving the basal cells. "IPA analysis of the HGF signature suggested sonic hedgehog signaling (P = 0.007), basal cell carcinoma signaling (P = 0.017), and tight junction signaling (P = 0.020) among other signaling pathways were upregulated by HGF signaling in cocultures." (PMID 24025166, 2013).
benign meningioma (1 paper, 2021). A grade I, slowly growing meningioma. "It was found that HGF and c-MET were significantly upregulated in malignant meningioma compared with benign meningioma." (PMID 34408780, 2021).
bile duct cancer (1 paper, 2018). "In a 3-D culture of bile duct cancer cells in collagen gel, HGF induced robust activation of MET, ERK, and AKT, which was associated with enhanced expression of genes involved in bile duct development and subsequent branching of tubulogenesis." (PMID 30322054, 2018).
Blindness (1 paper, 2015). Blindness is the condition of lacking visual perception defined as a profound reduction in visual perception. "Ocular localization of the proteins that showed significantly higher expression in the vitreous than in blood (CCL2, IGFBP2, MMP10, HGF, TNFRSF11B) was investigated in histological specimens of eyes from patients with painful blindness due to secondary glaucoma after CRVO." (PMID 25978399, 2015).
breast adenocarcinoma (1 paper, 2018). "In the pro-metastatic cell line 1833, derived from MDA-MB-231 breast adenocarcinoma cells, both hypoxia and hepatocyte growth factor (HGF) influence the effect of miR-125b on ETS proto-oncogene 1 transcription factor (ETS1)." (PMID 29700305, 2018). "In 1833 bone metastatic cells, derived from MDA-MB-231 breast adenocarcinoma cells, the effects of miR-125b on ETS1 activity and on the biological functions are influenced by HGF and hypoxia, which are stimuli of the bone microenvironment." (PMID 29700305, 2018).
Breast hypertrophy (1 paper, 2014). The presence of hypertrophy of the breast. "Based on these results, abnormal regulation of HGF secretion in mammary stroma may be a critical factor in breast hypertrophy." (PMID 24720804, 2014).
carcinoid tumour (1 paper, 2005). "In the present study, we employ transcript profiling to examine molecular mechanisms underlying proliferative responses in BON carcinoid tumour cells after exposure to gastrin, HGF, EGF and PACAP." (PMID 15846300, 2005). "Second, the novel finding that also HGF affects growth of carcinoid tumour cells is interesting considering the central role HGF plays as a growth regulator of other tumour cell types." (PMID 15846300, 2005).
carcinoids (1 paper, 2005). "By RT–PCR analysis, BON cells were shown to express mRNA of the HGF receptor (c-Met), indicating a possible role of HGF in controlling growth of carcinoids." (PMID 15846300, 2005). "This may indicate that the oncogenic potential of gastrin in carcinoid cells is at least as high as that of HGF." (PMID 15846300, 2005). "We here report the novel findings that HGF, EGF and PACAP all stimulate proliferation of carcinoid BON cells." (PMID 15846300, 2005).
cartilage disorders (1 paper, 2025). "Our results support the clinical translation of allogeneic synovial MSC therapy as an OA treatment and suggest that HGF pathway modulation could enhance therapeutic outcomes in regenerative medicine approaches for cartilage disorders." (PMID 41042750, 2025).
cerebral artery occlusion (1 paper, 2018). "The use of unmodified DPSCs and DPSCs overexpressing HGF was associated with improved motor function compared to that with administration of vehicle at 7 days post-transient middle cerebral artery occlusion." (PMID 30151417, 2018).
cerebral edema (1 paper, 2015). "It is suggested that HGF-mediated prevention of endothelial cell injury and maintenance of the tight junctional proteins in the endothelial cells may be a possible mechanism for the protective effect of HGF against the disruption of the BBB and the prevention of cerebral edema." (PMID 25574187, 2015).
cervix adenocarcinoma (1 paper, 2018). "Under normoxia, as expected, HGF/SF treatment of HeLa human cervix adenocarcinoma cells induced substantial phosphorylation of MET tyrosine residues Y1234/1235 and led to activation of the Akt and Erk kinases, as revealed by detection of their phosphorylated forms." (PMID 29930749, 2018).
chronic asthma (1 paper, 2014). An asthma that is characterized by the development of persistent airway inflammation and recurrent attacks of breathlessness and wheezing, which vary in severity and frequency. "In an experimental chronic asthma model, the subcutaneous administration of ONO-1301 increased pulmonary HGF expression, suppressed airway hyperresponsiveness, and improved airway remodeling/fibrotic change, while neutralization of HGF significantly abrogated the effects of ONO-1301." (PMID 28548072, 2014).
chronic hepatitis B (1 paper, 2024). "Studies have shown that serum HGF levels in patients with chronic hepatitis B may reflect viral load, necro-inflammatory activity in the liver." (PMID 38495649, 2024).
chronic liver failure (1 paper, 2024). Liver failure that develops slowly and gradually for some time, possibly for years, often as the result of cirrhosis, or malnutrition. "HGF is a growth factor that stimulates the proliferation of hepatocytes and several other cell types by activating the c-Met receptor, and it has been shown that UMSCs can promote liver regeneration in rats with acute-on-chronic liver failure through an increase in HGF expression." (PMID 38613627, 2024).
chronic skin ulcers (1 paper, 2018). "However, because proteolytic degradation of HGF impairs re-epithelialization in chronic skin ulcer patients and restricted the therapeutic effects of HGF, non-native MET-agonists containing macrocyclic peptides have an advantage in treating chronic skin ulcers." (PMID 30322054, 2018).
clear cell sarcoma (1 paper, 2015). A rare malignant neoplasm with melanocytic differentiation characterized by the presence of polygonal or spindle shaped clear cells. "Unfortunately we could not correlate our findings of HGF expression in clear cell sarcomas with MET immunohistochemistry due to limited tissue resources." (PMID 25844809, 2015).
colorectal adenocarcinoma (1 paper, 2014). The most common type of colorectal carcinoma. "Hepatocyte growth factor, which plays a critical role in the metastasis of HCC has been reported to induce not only scattering but also collective migration of colorectal adenocarcinoma cells." (PMID 25343336, 2014).
delirium (1 paper, 2025). A disorder characterized by confusion; inattentiveness; disorientation; illusions; hallucinations; agitation; and in some instances autonomic nervous system overactivity. "Overall, delirium was correlated with several cytokines (decreased IL-22, IL-21, IL-1α), chemokines (increased CXCL1, CCL11, CXCL13), and growth factors (increased HGF, and a tendency towards increased VEGF-A)." (PMID 41219650, 2025).